LECT2 (leukocyte cell derived chemotaxin 2)
Diseases named in the same sentence as LECT2 in open-access papers (continued):
Sharing a sentence is not in itself a finding about the gene and the disease.
tumor (32 papers, 2014 to 2026). "Using the murine ID8 EOC model, we verified that Lect2 directly acts on immature myeloid cells and that loss of Lect2 fosters MDSCs, together with M2-polarized macrophages, impairs innate and adaptive anti-tumor immunity." (PMID 38177412, 2024). "Using the murine EOC model, we discovered that loss of Lect2 promotes EOC progression by modulating both tumor cells and the tumor microenvironment." (PMID 38177412, 2024). "We evaluated the tumor development of ID8/Luc cells in Lect2-deficient C57BL/6J mice (Lect2+/− and Lect2−/−) and in their wild-type littermates (Lect2+/+)." (PMID 38177412, 2024). "Leukocyte cell-derived chemotaxin-2, a 16-kDa secreted protein encoded by the LECT2 gene, is involved in the regulation of the tumour microenvironment and plays a critical role in hepatic oncogenesis." (PMID 35574316, 2022). "In contrast, the deficiency of LECT2 in the MiaPaca-2 cells markedly speeded up tumor growth in vivo." (PMID 33937262, 2021). "Our study demonstrates that loss of Lect2 in the ApcMin/+ mouse had a significant pro-tumorigenic effect, confirming a protective tumour suppressor role for Lect2 in Wnt-driven CRC." (PMID 30559928, 2018). "In the liver, Lect2 has a protective anti-inflammatory role in β-catenin-induced tumorigenesis and loss of this chemokine results in tumour progression and metastatic disease." (PMID 30559928, 2018). "Samples from day 55 PI were analysed in order to investigate the effect of Wnt-activation and Lect2 loss on cytokine expression prior to tumour development." (PMID 30559928, 2018). "Taken together this indicates that the homozygous loss of Lect2 enhances tumour initiation and progression in the ApcMin/+ model independently of an effect on the Wnt pathway." (PMID 30559928, 2018). "To confirm mutations in β-catenin gene due to existing tumor heterogeneity and also verify corresponding Lect2 expression, we extracted both genomic DNA and total RNA from same nodules." (PMID 24892551, 2014). "Using mouse model, we confirmed that serum LECT2 levels indeed correlated with upregulation of Lect2 expression in the tumor that occurred secondary to β-catenin gene mutations in a murine HCC model." (PMID 24892551, 2014). "We next examined Lect2 mRNA expression as well as Glul mRNA (encoding GS protein) expression in these tumor nodules." (PMID 24892551, 2014). "Further analysis showed that the homozygous loss of Lect2 promoted intestinal tumorigenesis by changing the tumor microenvironment, indicated by altering the balance of pro- and anti-inflammatory cytokines and key regulators of the T-cell lineage in the Wnt-activated colorectal cancer model." (PMID 36969200, 2023). "Lect2 has been implicated as a novel Wnt repressor and a potential tumour suppressor in CRC." (PMID 30559928, 2018). "Based on these observations, we propose that serum Lect2 levels in mice may be an excellent non-invasive and simple modality to monitor tumor burden due to β-catenin gene mutations." (PMID 24892551, 2014). "Leukocyte-derived chemotaxin-2 (LECT2), secreted by hepatocytes, which is involved in pathogen clearance, inflammation and immune response, tumor metastasis in NASH." (PMID 41333471, 2025). "In this context, reintroducing LECT2 is a rational approach to efficiently circumvent the immunosuppressive EOC tumor microenvironment and thus boost the likelihood of response to immune checkpoint blockade." (PMID 38177412, 2024). "Specifically, there was a substantial increase of T cells in the spleen from Lect2+/+ EOC compared to their non-tumor-bearing counterparts (P < 0.01), while splenic T-cell recruitment in Lect2−/− EOC was negligible." (PMID 38177412, 2024). "Accumulating evidence supports a tumor-suppressive role of LECT2, given that uncontrolled inflammation is involved in cancer progression." (PMID 38177412, 2024). "Blockade of PD-L1 resulted in tumor rejection in 20% (3 of 15) of the Lect2+/+ EOC mice, leading to significantly longer survival (P < 0.05)." (PMID 38177412, 2024).
tumor (continued). "In turn, the ID8 tumor burden of Lect2−/− mice was significantly reduced upon Lect2 overexpression compared to the vector control (P < 0.01)." (PMID 38177412, 2024). "Decreased expression of LECT2 during EOC progression has profound effects on both tumor cells and tumor microenvironment and potentially impedes the success of immunotherapy in EOC." (PMID 38177412, 2024). "Other studies have shown that LECT2’s tumor inhibition can also be achieved by inhibiting HCC glycolysis." (PMID 38881894, 2024). "LECT2 plays an important role in inflammation, immune response and tumor development, so it has the potential to be a target for future therapies." (PMID 38881894, 2024). "Apart from directly interacting with cancer cells, LECT2 also modulates cancer progression via the tumor immune microenvironment (TIM)." (PMID 36969200, 2023). "Results from another study indicated that LECT2 is a crucial role in liver tumorigenesis as its absence alters the tumor phenotype and the tumor microenvironment suggested that LECT2 is a promising immunotherapeutic option for HCC." (PMID 36776357, 2022). "Based on TCGA analysis, tumor LECT2 expression was significantly lower in HCC patients with vascular invasion (microvascular and macrovascular invasions) than them without vascular invasion." (PMID 36055405, 2022). "Another study has found that LECT2 expression in HCC is strongly correlated with tumour angiogenesis." (PMID 35574316, 2022). "LECT2 is downregulated in metastatic PDACs compared with the primary tumor, and its expression is correlated with multiple clinical pathologic features and prognosis." (PMID 33937262, 2021). "In conclusion, the current study provides validating evidence that LECT2 acts as a tumor suppressor in PDAC, and the expression of LECT2 in PDAC cells and tissue is significantly lower, which predicts reduced survival." (PMID 33937262, 2021). "Subsequently, cell viability and colony formation assays were performed to examine the involvement of FOXM1 in the effect of LECT2 on tumor proliferation." (PMID 33937262, 2021). "Immunohistochemical staining showed that the expression level of LECT2 in the tumor was significantly lower than that in the adjacent area of the tumor." (PMID 33937262, 2021). "Down-regulated genes contain markers enriched in mature hepatocytes (Tat, Cyp7a1, Apoa5, Pck1, Cyp3a11, Mup3 or Acsl1) and tumor suppressors (Lect2, Wfdc17 or Efemp1)." (PMID 32372053, 2020). "Previous studies have identified a key role for Lect2 in the regulation of specific sub-populations of inflammatory cells and this function was key to the tumour suppressor role of Lect2 in β-catenin-activated HCC." (PMID 30559928, 2018). "Using this model, we identified a novel role for Lect2 as a tumour suppressor in Wnt-driven intestinal tumorigenesis." (PMID 30559928, 2018). "In conclusion, our data demonstrate a novel role for Lect2 as a tumour suppressor during Wnt-driven intestinal tumorigenesis." (PMID 30559928, 2018). "In the liver Lect2 has been shown to have a protective anti-inflammatory role in β-catenin-induced tumorigenesis and the role of Lect2 as a tumour suppressor in human HCC has been firmly established." (PMID 30559928, 2018). "As we previously identified upregulation of Lect2 the tumour suppression observed in the ApcMin/+Mbd2−/− we generated ApcMin/+Mbd2−/−Lect2−/− to clarify its role in this phenotype." (PMID 30559928, 2018). "In summary this data indicates that Lect2 plays a role in preventing tumour initiation in the ApcMin/+intestine." (PMID 30559928, 2018). "Increased LECT2 gene expression is specific to tumours induced by β-catenin, and activation of the LECT2 gene can lead to the development of tumours with a better prognosis." (PMID 28924246, 2017). "Previous studies have found that LECT2 targets to both immune and tumor cells to suppress HCC development and vascular invasion." (PMID 27507763, 2016).
tumor (continued). "Overall, we revealed a significant correlation between LECT2 expression and tumor angiogenesis in HCC progression." (PMID 27507763, 2016). "By using a NSG (NOD scid gamma; NOD.Cg-Prkdcscid Il2rgtm1Wjl/SzJ) immunocompromised mouse model, in which almost all of the immune cells are lost, we excluded the potential immunomodulatory effects of LECT2 on tumor inhibition." (PMID 27507763, 2016). "In the present study, we further demonstrated that LECT2 suppressed tumor angiogenesis, inhibiting tumor growth in immunodeficient HCC mouse model." (PMID 27507763, 2016). "Collectively, clinical and mechanistic findings from our own and other studies suggest that LECT2 is an important regulator of tumor growth during HCC development and progression." (PMID 27507763, 2016). "In our analysis, we were unable to detect any correlation between serum LECT2 levels and differentiation status of the tumor." (PMID 24892551, 2014). "To address if serum LECT2 levels showed any correlation with LECT2 expression in the tumors, we selected a group of 28 patients for which had serum and corresponding tumor tissue." (PMID 24892551, 2014). "In a mouse liver tumor model, LECT2 prohibits tumor progression by regulating Th2-based inflammation." (PMID 24892551, 2014). "We next tested whether the reduction of Lect2-mediated immune decline in the tumor microenvironment could impair PD-1/PD-L1 immunotherapy for EOC tumors." (PMID 38177412, 2024). "In addition to IL-10 and VEGF in the EOC tumor microenvironment, our results indicate that Lect2 is another novel modulator of PD-L1 expression in MDSC." (PMID 38177412, 2024). "We further explored the relationship between LECT2 and the tumor immune microenvironment." (PMID 36160006, 2022). "Among the other hepatokines investigated in our study, high levels of AHSG, IGFBP1 and IGFBP-2 are found in the serum and HCC tissues of patients, whereas LECT2 expression is usually decreased and appears to behave as a tumour suppressor under the control of beta-catenin in the liver." (PMID 35409319, 2022). "Thus, the effect of LECT2 gene therapy on tumor vasculature was investigated by histological analysis." (PMID 36055405, 2022). "By inhibiting angiogenesis, LECT2 inhibits tumor growth in HCC." (PMID 36160006, 2022). "Moreover, LECT2 deletion promotes the infiltration of inflammatory and immature monocytes with immunosuppressive capacities and tumor-promoting potential." (PMID 36055405, 2022). "The results suggested that Lect2 expression may affect the level of multiple immune cell infiltration in the tumor microenvironment of HCC." (PMID 36160006, 2022). "Moreover, we show exogenous LECT2 treatment inhibited CSC functions such as tumor sphere formation and drug efflux." (PMID 36055405, 2022). "Finally, we also analyzed the expression level of LECT2 in the PADC tumor and the adjacent area of the tumor." (PMID 33937262, 2021). "In vivo studies showed that LECT2 overexpression inhibits tumor growth and lung metastasis." (PMID 33937262, 2021). "Since LECT2 expression is downregulated in metastatic PDACs compared with the primary tumor, we speculated that LECT2 might be involved in the regulation of PDAC metastasis." (PMID 33937262, 2021). "This work may give some clues to the potential of LECT2 as a biomarker or therapeutic target in tumor formation and metastasis of PDAC." (PMID 33937262, 2021). "In order to analyse whether the tumour suppressor function of Lect2 in Wnt-driven tumorigenesis is due to its role in inflammation we measured key cytokine levels in our Wnt-activated models of CRC." (PMID 30559928, 2018). "As Lect2 was previously indicated to function as a Wnt repressor we hypothesised that the tumour suppressor role of Lect2 may be due to a protective inhibitory function in the initiating stages of Wnt deregulation." (PMID 30559928, 2018).
tumor (continued). "To determine whether LECT2 affects tumor growth, we used an immunodeficient NSG mouse model of HCC subcutaneously injected with LECT2-overexpressing SK-Hep1 (SK-Hep1/LECT2) cells." (PMID 27507763, 2016). "Here, we sought to determine the role of LECT2 in tumor angiogenesis in HCC patients." (PMID 27507763, 2016). "We found that LECT2 expression inhibited tumor growth via angiogenesis in the HCC xenograft model." (PMID 27507763, 2016). "We first demonstrated that LECT2 suppressed HCC growth by inhibiting tumor angiogenesis in vivo." (PMID 27507763, 2016). "All 3-tumor nodules had high Lect2 and Glul expressions as compared to the background liver." (PMID 24892551, 2014). "Although further investigations are required, our finding of a significant decrease in ascites volume in tumor-bearing mice with high Lect2 levels suggests that maintaining the amount of regional or circulating Lect2 may help ease the ascites formation by acting on these receptors." (PMID 38177412, 2024). "In Ctnnb‐1 mutated HCC model, the absence of LECT2 in tumour hepatocytes contributed to the EMT (epithelial to mesenchymal transition) of cancer cells and the recruitment of immature inflammatory monocytes that possessed immunosuppressive properties and tumour‐promoting potential." (PMID 35656863, 2022). "However, the additional loss of Lect2 failed to reverse the suppression of tumour initiation observed in the ApcMin/+Mbd2−/− mice indicating Lect2 does not play a significant role in the suppression of intestinal tumourigenesis observed in that model." (PMID 30559928, 2018). "Therefore, LECT2 could inhibit both tumor growth and metastasis by simultaneously targeting MET and VEGFR2 in HCC patients." (PMID 27507763, 2016). "Finally, we evaluated the correlation of LECT2 expression with tumor angiogenesis in HCC patients." (PMID 27507763, 2016). "Since anti-β-catenin drug discovery is a timely concept, and models like DEN/PB may be of essence in testing anti-β-catenin therapies, our studies demonstrate the suitability of assessing serum Lect2 levels in such models to monitor tumor response to experimental therapies." (PMID 24892551, 2014). "Furthermore, despite β-catenin activation observed in an additional subset of non-CTNNB1 mutated HCC, which showed high LECT2 expression, serum LECT2 levels were not predictive for active β-catenin signaling in the tumor." (PMID 24892551, 2014). "However, in HCC patients, serum LECT2 levels were not significantly different in tumor with CTNNB1 or without CTNNB1 mutations when compared to patients with chronic liver disease or healthy volunteers." (PMID 24892551, 2014). "In summary, we have elucidated an emerging role of LECT2 in EOC, which suppresses tumor progression." (PMID 38177412, 2024). "Our research found that LECT2 is a protective factor for HCC, which is consistent with the previous conclusion that LECT2 acts as a tumor suppressor." (PMID 37239939, 2023). "An oncogenic β-catenin-triggering inflammatory tumor microenvironment is indispensable for the aggressiveness of HCC in mice, and LECT2 inhibits HCC progression by blocking β-catenin-induced inflammation by interconnecting with invariant NKT (iNKT) cells." (PMID 36969200, 2023). "A previous study mentioned that LECT2 inhibited not only the cell migration and invasion in human HCC cell lines but also the tumor growth in the xenograft animal model." (PMID 36055405, 2022). "To further explore the effect of LECT2 on metastasis in a physiologic tumor context, we developed a xenograft model, employing BXPC-3 cells expressing LECT2 vectors." (PMID 33937262, 2021). "In this study, we for the first time showed that LECT2, SLC10A1, CYP3A4, and HSD17B13 can suppress HCC tumor growth by inhibiting Warburg effect." (PMID 32576292, 2020).
tumor (continued). "In addition, the role of Lect2 in inflammation and the potential of this chemokine to affect intestinal tumour development by altering the inflammatory response is of significant interest and may aid the identification of novel targets in the treatment of this disease." (PMID 30559928, 2018). "All of these findings suggest that LECT2 is a novel antiangiogenic factor and suppresses VEGF165-induced angiogenesis and tumor growth in HCC patients." (PMID 27507763, 2016). "In comparison, B cell recruitment in the spleen was not remarkable in tumor-bearing Lect2+/+ and Lect2−/− mice." (PMID 38177412, 2024). "We further revealed that Arg-1 (P < 0.001), NOX-2 (P < 0.05), TGF-β (P < 0.05), and PD-L1 (P < 0.05) were significantly higher from Lect2−/− EOC than Lect2+/+ EOC, supporting their potential for inhibiting the tumor-infiltrating lymphocytes and silencing the immune response." (PMID 38177412, 2024). "Based on the tumor-suppressive function of LECT2 gene delivery by Ad in rat Novikoff HCC model, the effect of Ad-LECT2 infection on cell viability and apoptosis was further investigated in rat N1-S1 cells." (PMID 36055405, 2022). "Other studies reported that IL-37, LECT2, and TNFSF15 suppress tumor growth." (PMID 35563525, 2022). "Overall, these observations indicated that LECT2 might antagonize FOXM1 signaling via targeting HGF/MET, which affects multiple biological processes and slow down PDAC tumor formation and metastasis." (PMID 33937262, 2021). "In this study, we found that LECT2 suppressed tumor growth in vivo without affecting cancer cell proliferation in vitro." (PMID 27507763, 2016). "On the basis of these findings, we hypothesized that LECT2 not only suppresses vascular invasion and metastasis of HCC cells but also inhibits tumor growth by targeting stromal cells." (PMID 27507763, 2016). "In this study, we found that treatment with LECT2 inhibited tumor growth but not cancer cell proliferation in a xenograft mice model of HCC." (PMID 27507763, 2016). "Strikingly, the 9 mice with evidence of histological tumor burden showed significantly (p<0.01) higher serum Lect2 levels (55.9±19.9 ng/mL) as compared to the 4 non-tumor bearing mice (24.9±5.5 ng/mL)." (PMID 24892551, 2014). "As our data shows that Lect2 modulates Wnt-driven tumorigenesis, but does not appear to directly effect Wnt-signalling in developed tumours we next addressed whether Lect2 may have a key role during the very early stages of Wnt-activation." (PMID 30559928, 2018). "LECT2 is a tumor suppressor in HCCs16 but it is not yet clear whether LECT2 also regulates the angiogenic activity in specific tissues." (PMID 27507763, 2016).